MBP (myelin basic protein)
Diseases named in the same sentence as MBP in open-access papers (continued):
Sharing a sentence is not in itself a finding about the gene and the disease.
bipolar disorder (8 papers, 2012 to 2023). A disorder of the brain that causes unusual shifts in mood, energy, activity levels and the ability to carry out day-to-day tasks. "The level of MBP-hydrolyzing activity of IgG from patients with bipolar disorder was statistically significantly 1.6-folds higher than that of healthy individuals." (PMID 35806400, 2022). "Analysis of the level of MBP-hydrolyzing activity of IgG in patients with bipolar disorder revealed a statistically significant (p = 0.003) increase in activity by 1.6 times, compared with healthy individuals." (PMID 35806400, 2022). "The median values of the MBP-hydrolyzing activity level were 9.33 (0.23; 25.46) in bipolar disorder and 5.71 (0.00; 9.88) in the healthy control group." (PMID 35806400, 2022). "In this work, we discovered antibodies hydrolyzing myelin basic protein from the serum of patients with bipolar disorder and described their biochemical properties." (PMID 35806400, 2022). "The ability of serum IgG to hydrolyze MBP in bipolar disorder, which we have revealed, may become an additional link between the processes of myelin damage and inflammation in bipolar disorder." (PMID 35806400, 2022). "The ability of serum IgG to hydrolyze MBP in bipolar disorder, which we have revealed, may become an additional link between myelin damage and inflammation." (PMID 35806400, 2022). "The ability of serum IgG to hydrolyze MBP in bipolar disorder may become an additional link between the processes of myelin damage and inflammation." (PMID 35806400, 2022).
brain injury (8 papers, 2015 to 2023). Acute and chronic (see also brain INJURIES, CHRONIC) injuries to the brain, including the cerebral hemispheres, CEREBELLUM, and brain STEM. "The results obtained by LFB and MBP staining suggest that the myelination of surviving axons in the OT was mostly preserved at the investigated time point after the last brain trauma." (PMID 34205342, 2021). "In patients with traumatic brain injury, significant MBP elevation in blood samples drawn within hours of the ictus predicts non-survivors as well as CT scan evidence of intracranial bleeding or diffuse axonal injury." (PMID 31915942, 2020). "Consequently, this study investigated the clinical value of MBP and 8-oxo-dG in the early postnatal period for different types of brain injuries in very preterm." (PMID 36349194, 2022). "Other promising biomarkers have been suggested for diagnosis, monitoring and prognosis of traumatic brain injury (TBI) such as microtubule-associated protein-2 (MAP2, neuron-specific enolase (NSE), myelin basic protein (MBP), tau, s100β and neurofilament heavy chain protein (NF-H)." (PMID 30596792, 2018). "The expression levels of myelin basic protein are widely considered to be closely correlated with the severity of the brain trauma; however, not all studies have supported this view." (PMID 25667676, 2015).
dementia (8 papers, 2014 to 2024). Loss of intellectual abilities interfering with an individual's social and occupational functions. "Specifically, deamidation of the glutamine residue 82 in the MBP degenerative epitope was associated with impaired degradation and accumulation of degenerated protein in the temporal lobe of women with dementia." (PMID 26983404, 2016). "Our data now indicate that gender influences on the dementia-associated deamidation of MBP may alter protein degradation in the temporal lobe of AD + CVD patients." (PMID 26983404, 2016). "Contrary to our result, MBP concentration decreased with increasing post-mortem interval in a study on vascular white matter changes and dementia." (PMID 35765081, 2022). "In particular, we observed that hyper-citrullination and hyper-deamidation of MBP were prevalent in female dementia patients." (PMID 26983404, 2016). "When compared with controls, AD + CVD patients exhibited increased ratio of deamidation in brain MBP, and this was more extensive in women than in men, particularly at residues Gln 281, 255, 236 and 215, suggesting increased incidence of DPMs in women with dementia." (PMID 26983404, 2016). "The increased production of MOG and MBP antibodies in serum and CSF suggest altered activity in DLB’s acquired immune system, making it different from other types of dementia." (PMID 34393763, 2021). "Biochemical studies on WM specimens from AD patients demonstrated that CNS myelin-related components, such as myelin basic protein (MBP) and cholesterol, are significantly decreased compared to individuals without dementia." (PMID 38377028, 2024). "Several dementia-specific citrulline residues were also identified in soluble proteins previously categorized as pro-immunogenic, which include the receptor P2X7, alpha-internexin, GFAP, CNP, MBP, and histones." (PMID 28865468, 2017).
encephalomyelitis (7 papers, 2007 to 2025). Inflammation of the brain and the spinal cord. "Sharing of a 6-aa long peptide between hepatitis B virus DNA polymerase and myelin basic protein was enough to induce experimental encephalomyelitis in rabbits." (PMID 32411933, 2020). "This suggests that MBP specific T cells may cause encephalomyelitis also in humans, but does not pinpoint MBP specific T cells as culprits in MS." (PMID 22069614, 2010). "EAE is initiated by introducing a specific CNS antigen, such as MOG, myelin basic protein (MBP), or proteolipid protein (PLP), in the context of an inflammatory stimulus to induce encephalomyelitis." (PMID 33224094, 2020).
melanoma (7 papers, 2015 to 2025). A malignant, usually aggressive tumor composed of atypical, neoplastic melanocytes. "The potential involvement of the JAK2-NLRP3 axis, implicated in melanoma regulation and immune modulation, further emphasizes the complexity and breadth of MBP’s therapeutic actions by modulating JAK/STAT pathways." (PMID 40508400, 2025). "Colony formation assays further confirmed MBP’s inhibitory effects, showing a significant reduction in the clonogenic potential of both melanoma cell lines, suggesting the suppression of long-term proliferative potential." (PMID 40508400, 2025). "After removing duplicates, these melanoma-related genes were intersected with the 322 MBP targets, yielding 61 overlapping genes, which were recognized as potential therapeutic targets for MBP in melanoma treatment." (PMID 40508400, 2025). "Based on these findings, the role of the JAK1/STAT1 pathway in MBP-treated melanoma cells was experimentally validated by Western blot analysis." (PMID 40508400, 2025). "Network pharmacology analysis combined with experimental validation indicated that MBP exerts its anti-melanoma effects through multiple targets and pathways, prominently involving the JAK1/STAT1 signaling pathway." (PMID 40508400, 2025). "Both short-term proliferation assays and long-term colony formation experiments consistently revealed MBP’s capacity to suppress melanoma cell growth, supporting its potential as a candidate for further preclinical evaluation." (PMID 40508400, 2025). "Despite Xinyi’s established therapeutic uses, MBP’s potential in melanoma treatment remains largely unexplored, warranting further investigation to uncover its active components and mechanisms of action." (PMID 40508400, 2025). "The melanoma-related targets of MBP were integrated into the STRING database to analyze protein–protein interactions." (PMID 40508400, 2025). "These combined computational and experimental findings highlight naringenin’s potential therapeutic relevance through the modulation of the JAK1–STAT1 signaling pathway, reinforcing its role as an active anti-melanoma constituent of MBP." (PMID 40508400, 2025). "By integrating metabolomics with network pharmacology, we elucidated the potential mechanisms through which MBP exerts its anti-melanoma effects." (PMID 40508400, 2025). "Naringenin significantly suppressed melanoma cell colony formation and migration, underscoring its pivotal role in mediating MBP’s anti-melanoma activity." (PMID 40508400, 2025). "Overall, this study provides comprehensive evidence supporting MBP’s potential as an anti-melanoma therapeutic agent." (PMID 40508400, 2025). "In this study, the phytochemical composition, antioxidant activity, and anti-melanoma mechanisms of MBP extracts were systematically investigated." (PMID 40508400, 2025). "Notably, STAT3 and STAT1 were among the top-ranked targets, further supporting the potential involvement of the JAK-STAT signaling pathway in MBP’s anti-melanoma activity." (PMID 40508400, 2025). "Previous studies have shown that extracts rich in quinic acid exhibit significant anti-melanoma effects, including the inhibition of melanoma cell growth and the induction of apoptosis, supporting quinic acid’s role as a potential bioactive component in MBP’s therapeutic effects." (PMID 40508400, 2025). "To investigate the potential mechanisms of MBP in melanoma treatment, we conducted GO and KEGG enrichment analyses to identify melanoma-related biological processes (BPs), cellular components (CCs), and molecular functions (MFs) associated with the identified targets." (PMID 40508400, 2025). "UHPLC-Q-Exactive Orbitrap MS analysis identified 26 compounds within MBP, suggesting that its observed anti-melanoma activity may stem from synergistic interactions among multiple phytochemical constituents." (PMID 40508400, 2025).
melanoma (continued). "Bioinformatics and topological analyses further identified the key targets and pathways modulated by MBP, findings that were subsequently validated via in vitro experiments demonstrating that both MBP and its active compound, naringenin, effectively inhibit melanoma cell proliferation and migration." (PMID 40508400, 2025). "Taken together, these findings suggest that naringenin may contribute to the overall anti-melanoma activity observed in MBP, potentially through multiple mechanisms." (PMID 40508400, 2025). "Indeed, MBP+ eosinophils have been found to clear metastatic melanoma cells in the mouse lungs, whereas the lysates of MBP+ eosinophils have turned out cytotoxic in vitro when co-cultured with cancer cells." (PMID 34691082, 2021). "Additionally, wound healing assays indicated that MBP significantly inhibited melanoma cell migration, suggesting that MBP may potentially impede tumor metastasis." (PMID 40508400, 2025). "The CCK-8 results revealed that MBP extract inhibited the proliferation of both B16F10 mouse melanoma cells and A375 human melanoma cells in a concentration-dependent manner across the range of 12.5–800 μg/mL." (PMID 40508400, 2025). "Western blot analysis confirmed MBP significantly inhibited the phosphorylation of JAK1 and STAT1 in melanoma cells." (PMID 40508400, 2025). "In vitro assays demonstrated that MBP and naringenin inhibited the proliferation and migration of A375 and B16F10 melanoma cells, while exhibiting relatively low cytotoxicity toward normal keratinocytes." (PMID 40508400, 2025). "The experimental results demonstrated MBP’s anti-proliferative and anti-migratory effects on melanoma cells, accompanied by relatively low cytotoxicity to non-cancerous HaCaT keratinocytes." (PMID 40508400, 2025). "In contrast, normal human HaCaT keratinocytes maintained over 90% viability within the 12.5–200 μg/mL range, indicating that MBP preferentially affects melanoma cells while having lower cytotoxic effects on non-cancerous cells." (PMID 40508400, 2025). "Treatment with MBP significantly reduced the migration of both B16F10 and A375 melanoma cell lines." (PMID 40508400, 2025). "Future investigation is needed into whether MBP can directly modulate JAK and STAT activation and lead to enhanced tumor suppression in melanoma." (PMID 40508400, 2025). "Immunocytochemical detection of MBP did not reveal its expression in the treated melanoma cells, thus refuting the neurogenic differentiation of the treated melanoma cells." (PMID 35458039, 2022). "Expression of Mbp by melanoma cells is somewhat surprising, but it has been shown that B16F10 cells undergo differentiation to a myelinating glial phenotype characterized by induction of the transcriptional activity of the MBP promoter." (PMID 26605345, 2015).
autoimmune encephalitis (6 papers, 2011 to 2025). Inflammation of the brain secondary to an immune response triggered by the body itself. "Human Tregs have been designed to express the Ob2F3 TCR V region to target myelin basic protein (MBP), and experiments suggest that these ob2f3-expressing Treg cells ameliorate experimental autoimmune encephalitis in transgenic mice." (PMID 39734406, 2024). "MBP-specific CD4 T-cells isolated from spleen and liver of mice transgenic for MBP expressed in hepatocytes proliferated, and a regulatory phenotype resulted, leading to suppression of experimental autoimmune encephalitis caused by autoreactive CD4 T-cells." (PMID 21779338, 2011). "Aquaporin-4 (AQP 4), myelin oligodendrocyte glycoprotein (MOG), myelin basic protein (MBP IgG), and autoimmune encephalitis-related antibodies were negative." (PMID 39911384, 2025). "The results of the autoimmune encephalitis antibodies, AQP 4 antibodies, and anti-myelin basic protein antibodies in the CSF and serum were negative in all children." (PMID 36352355, 2022).
COVID-19 (6 papers, 2023 to 2025). A disease caused by infection with severe acute respiratory syndrome coronavirus 2. "Elevated levels of IgA autoantibodies against amyloid β peptide, acetylcholine receptor, dopamine 2 receptor, myelin basic protein, and α-synuclein were detected in COVID-19 patients compared with healthy controls." (PMID 36832180, 2023). "Neurological manifestations in COVID-19 patients have been associated with the presence of autoantibodies against contactin-associated protein 2 (anti-Caspr2), GD1b ganglioside (anti-GD1b), myelin oligodendrocyte glycoprotein (anti-MOG), and myelin basic protein (anti-ObM)." (PMID 41009363, 2025). "Recent studies reveal elevated levels of brain-reactive autoantibodies against MBP, MOG, tubulin, CP2, and synaptophysin in patients suffering from protracted COVID-19, suggesting a possible involvement of neuroautoimmune pathophysiology." (PMID 38560433, 2024). "Levels of antibodies against the acetylcholine receptor (IgA), α-synucleins (IgA), amyloid β peptide (IgA), D2 receptor (IgA), and myelin basic protein (IgA) were elevated in COVID-19 patients’ sera regardless of disease severity." (PMID 36832180, 2023). "Our study also found several antibodies that were elevated in the sera of COVID-19 patients regardless of disease severity, including the acetylcholine receptor (IgA), α-synucleins (IgA), amyloid β peptide (IgA), dopamine 2 (D2) receptor (IgA), and myelin basic protein (IgA)." (PMID 36832180, 2023).
hematoma (6 papers, 2016 to 2022). A hematoma is a collection of blood from a vascular structure into an extravascular space. "Our study demonstrated that 5-BDBD can prevent the decrease in the mean fluorescence intensity of MBP in the peri-hematoma region after ICH days 3 and 7, showing that the P2X4R inhibitor 5-BDBD attenuated WMI induced by ICH." (PMID 34425835, 2021). "The coronal sections showed a progressive, overt decrease based on staining for normal MBP expression in the peri-hematoma region on D1 and D3 after ICH, and the immunofluorescence gradually recovered on D7 and D14." (PMID 31057367, 2019). "The results of Immunofluorescence showed intracerebral hematoma led to a demyelinating lesion (lower intensity of MBP) on the projecting axons via hematoma at 24 and 72 hours after ICH." (PMID 29088731, 2017). "CEGI treatment significantly alleviated the neurobehavioral dysfunction, reduced the lateral ventricular enlargement, promoted hematoma absorption, effectively up-regulated MBP/MAP-2 expression, and ameliorated white matter fiber damage post-ICH induction." (PMID 27782218, 2016). "We previously showed a progressive, dramatic decrease in staining for normal MBP and a concomitant increase in damaged MBP in the peri-hematoma region from 1 to 7 days after ICH." (PMID 26743212, 2016). "Furthermore, the double staining of MBP and DHE images showed that the ROS level around hematoma was evidently increased in ICH group, while it was profoundly decreased with the application of 5 mg/kg DPX." (PMID 35965685, 2022).
relapsing-remitting MS (6 papers, 2015 to 2022). "Anti-MBP antibodies have been detected not only in sera, but also in the cerebrospinal fluid (CSF) in 85% relapsing-remitting MS patients and 45% MS patients, respectively, compared to 2% in non-MS controls." (PMID 35795217, 2022). "Glatiramer acetate is an immunomodulatory agent based on the amino acid structure of myelin basic protein (MBP) that is currently used for the treatment of relapsing-remitting multiple sclerosis." (PMID 25767435, 2015).
rheumatoid arthritis (6 papers, 2011 to 2023). A chronic, systemic autoimmune disorder characterized by inflammation in the synovial membranes and articular surfaces. "Association of MBP locus with rheumatoid arthritis in the Japanese population." (PMID 21673997, 2011).
Arthritis (5 papers, 2008 to 2021). Inflammation of a joint. "All the mice developed arthritis in the control group, whereas a significant decrease in the incidence of arthritis was observed in MBP-C5a vaccinated group." (PMID 20975959, 2010). "Vaccination of mice with MBP-C5a led to significant reduction of arthritis incidence and severity but not anti-collagen antibody synthesis." (PMID 20975959, 2010).
colitis (5 papers, 2007 to 2022). Inflammation of the colon. "In this study, the staining results of NeuN and MBP in the colon indicate DSS-induced neuron damage and myelin loss of glial cells in the mice colitis model." (PMID 36189321, 2022). "The fluorescence intensity of MBP and NeuN decreased after DSS modeling (compared with the control group, p<0.01), suggesting that colitis induced neuron loss and myelin sheath injury of oligodendrocytes." (PMID 36189321, 2022). "Autoimmune disorders of thyroiditis, colitis, myelin basic protein autoantibodies, and diabetes are prevalent in children with ASD." (PMID 17207275, 2007). "In this group of autistic children, 7/25 (28%) had thyroiditis, 8/25 (32%) had colitis, 8/25 (32%) had PANDAS (Pediatric acquired neurological disorder associated with streptococcus), 20/25 (80%) had allergic diseases, and 7/25 (28%) were positive for serum antibodies to myelin basic protein." (PMID 17207275, 2007). "To that end, we previously showed that total B cell depletion led to a break in tolerance as indicated by reduced numbers of Treg and the onset of spontaneous EAE in MBP-TCR transgenic mice and acceleration of colitis onset in Il10−/− mice." (PMID 30643147, 2019).
Iron deficiency (5 papers, 2017 to 2024). "Extensive research in rodent models of early-life iron deficiency suggests lifelong alterations in myelin fatty acid profiles and gene expression for myelin basic protein, despite iron repletion later in life." (PMID 29375469, 2017). "Iron deficiency in rats caused a drop in MBP, PLP, lipids, and cholesterol." (PMID 36009098, 2022). "Additionally, postnatal iron deficiency in rats resulted in decreased concentrations of myelin basic protein and 2′,3′-cyclic nucleotide 3′-phosphohydrolase (CNPase), both of which increase as myelination occurs." (PMID 29375469, 2017). "Two studies focusing on iron deficiency have shown that deficits in recognition memory could be mitigated by prenatal choline supplementation, possibly by preserving hippocampal brain-derived neurotrophic factor and myelin basic protein expression." (PMID 32531929, 2020).